ALB (albumin)
Description:
Binds water, Ca(2+), Na(+), K(+), fatty acids, hormones, bilirubin and drugs (Probable). Its main function is the regulation of the colloidal osmotic pressure of blood (Probable). Major zinc transporter in plasma, typically binds about 80% of all plasma zinc. Major calcium and magnesium transporter in plasma, binds approximately 45% of circulating calcium and magnesium in plasma (By similarity). Potentially has more than two calcium-binding sites and might additionally bind calcium in a non-specific manner (By similarity). The shared binding site between zinc and calcium at residue Asp-273 suggests a crosstalk between zinc and calcium transport in the blood (By similarity). The rank order of affinity is zinc > calcium > magnesium (By similarity). Binds to the bacterial siderophore enterobactin and inhibits enterobactin-mediated iron uptake of E.coli from ferric transferrin, and may thereby limit the utilization of iron and growth of enteric bacteria such as E.coli. Does not prevent iron uptake by the bacterial siderophore aerobactin.
Synonyms: PRO0903; FDAHT; HSA; PRO0883; PRO1341
Tractability: Small molecule: a structure with a bound ligand is known; a high-quality ligand is known; it has a high-quality binding pocket; it belongs to a druggable protein family. Antibody: its Gene Ontology location is reachable by antibodies, with high confidence; UniProt places it where antibodies can reach, with medium confidence; UniProt predicts a signal peptide or a membrane-spanning region. PROTAC: ubiquitination databases record sites on it; its protein half-life has been measured; a small molecule that binds it is known.
Target class: Secreted protein
Gene: Protein-coding gene on chromosome 4 (73,397,114 to 73,426,607, forward strand). Ensembl gene ENSG00000163631.
Subcellular location: Secreted
Subcellular location (Human Protein Atlas): Endoplasmic reticulum; Golgi apparatus; Predicted to be secreted
Pathways (Reactome):
Drug ADME: Aspirin ADME; Ciprofloxacin ADME; Prednisone ADME
Metabolism: Heme biosynthesis; Heme degradation; Recycling of bile acids and salts
Metabolism of proteins: Post-translational protein phosphorylation; Regulation of Insulin-like Growth Factor (IGF) transport and uptake by Insulin-like Growth Factor Binding Proteins (IGFBPs)
Cellular responses to stimuli: Cytoprotection by HMOX1
Hemostasis: Platelet degranulation
Transport of small molecules: HDL remodeling
Vesicle-mediated transport: Scavenging of heme from plasma
Gene Ontology:
Molecular function: DNA binding; enterobactin binding; exogenous protein binding; fatty acid binding; heme binding; identical protein binding; molecular carrier activity; oxygen binding; protein binding; protein-folding chaperone binding; pyridoxal phosphate binding; toxic substance binding; antioxidant activity; copper ion binding
Biological process: cellular response to calcium ion starvation; cellular response to starvation; negative regulation of mitochondrial depolarization; cellular response to oxidative stress; heme biosynthetic process; heme catabolic process; response to nutrient levels; bilirubin transport; cellular oxidant detoxification
Cellular component: blood microparticle; extracellular exosome; extracellular region; nucleus; protein-containing complex; endoplasmic reticulum lumen; platelet alpha granule lumen; cytoplasm
Genetic constraint (gnomAD): Loss-of-function variants: 29 observed, 68.48 expected, observed/expected ratio (o/e) 0.42, 90% interval 0.31 to 0.58. The upper end of that interval is the gene's LOEUF score, 0.58, which puts it in group 2 of 6, group 1 being the genes least tolerant of losing a copy. Missense variants: 647 observed, 721.53 expected, observed/expected ratio (o/e) 0.9, 90% interval 0.84 to 0.96. Synonymous variants: 244 observed, 253.87 expected, observed/expected ratio (o/e) 0.96, 90% interval 0.87 to 1.07.
Gene-disease validity (ClinGen):
ClinGen rates the evidence that ALB causes each of these diseases.
congenital analbuminemia (autosomal recessive): Definitive. Congenital analbuminemia (CAA) is characterized by the absence or dramatic reduction of circulating human serum albumin (HSA).
hyperthyroxinemia, familial dysalbuminemic (autosomal dominant): Moderate.
Homologues: Orthologues: chimpanzee ALB (99% identical), macaque ALB (93% identical), rabbit ALB (75% identical), pig ALB (74% identical), rat Alb (74% identical), guinea pig ALB (73% identical), mouse Alb (72% identical), dog ALB (64% identical), tropical clawed frog alb (39% identical). Paralogues in human: AFP (39% identical), AFM (35% identical), GC (18% identical).
Diseases named in the same sentence as ALB in open-access papers:
ALB is named in the same sentence as 1,521 diseases in open-access papers, as found by Europe PMC text mining. Sharing a sentence is not in itself a finding about the gene and the disease. The quoted sentences say what the papers report.
diabetes (3,298 papers, 2003 to 2026). "Critically, liver-specific markers (NFS: mean |SHAP| = 0.0299; albumin: 0.0289) demonstrated superior predictive capacity compared to traditional cardiovascular risk factors (hypertension: 0.0145; diabetes: 0.0107; smoking: 0.0035)." (PMID 41942372, 2026). "Additional factors linked to significant CAD included age, smoking status, diabetes, hypertension, eGFR, urinary albumin, phosphate, LDL-cholesterol, hsCRP, and intact PTH." (PMID 41597410, 2026). "Age, sex, diabetes, physical activity, and serum albumin levels were independently associated with ASB among community-dwelling Korean adults." (PMID 41843590, 2026). "It is consistently associated with older age, female sex, diabetes, lower serum albumin, cardiovascular disease, longer dialysis vintage, and lower physical activity." (PMID 42042096, 2026). "Duration of diabetes and urine albumin-to-creatinine ratio were significantly associated with DR progression (hazard ratio 1.07 (95% confidence interval 1.02-1.12) and 1.03 (95% confidence interval 1.01-1.06), respectively)." (PMID 41816681, 2026). "Both our and literature results support the choice of isolated albumin as a more reliable substrate to study real diabetes-associated events that depend on diabetes stage." (PMID 41321387, 2025). "The positive association between DI-GM and serum albumin levels was consistent across most subgroups, with stronger effects observed in males, smokers, individuals with lower BMI, and those with diabetes." (PMID 40396178, 2025). "Carotid VC score over 4 was an independent predictor of all-cause and cardiovascular mortality, along with diabetes, low albumin, and high CRP." (PMID 40136613, 2025). "A hallmark of deteriorating kidney function in diabetes is increased albumin and protein levels in the urine (albuminuria and proteinuria), coupled with a decrease in serum albumin concentration." (PMID 41394924, 2025). "When we added adiponectin, glycated albumin, triglycerides, parental diabetes history, BMI, and use of cholesterol-lowering medication, which is known to increase diabetes risk, the prediction was significantly improved." (PMID 40218874, 2025). "Both studies indicated associations between fibrosis and age, platelets, diabetes, hypertension, waist circumference, hematocrit and, to a less pronounced extent in the current study, prothrombin time, albumin and white blood cells." (PMID 39702686, 2025). "The 15 models had Common risk factors for the 15 models included diabetes duration, age, glycosylated hemoglobin, serum creatinine and urinary albumin creatinine ratio." (PMID 40717809, 2025). "Preoperative parameters such as diabetes, chronic renal disease, low hemoglobin, lymphocyte, and albumin levels, and high LDH levels were associated with postoperative pneumonia." (PMID 39857079, 2025). "Meta-analysis of 21 influencing factors showed that Age, BMI, Pathological stage, Hemoglobin, Lymphocyte, Diabetes, Liver function, Radiotherapy history, Chemotherapy regimen, Gene factors and Albumin were 11 Risk factors for CIM." (PMID 41438123, 2025). "This study aimed to examine the correlation between the serum urea nitrogen to albumin ratio and cardiovascular diseases, cardiovascular mortality, and all-cause mortality in diabetes." (PMID 40290308, 2025). "The prevalence of diabetes mellitus was significantly higher in the low-risk group (91.7% vs. 50.0%, p < 0.05), and serum albumin levels were also significantly higher in the low-risk group (3.3 vs. 2.3 g/dL, p < 0.05)." (PMID 40943970, 2025). "Kidney function was significantly associated with diabetes mellitus, decreased serum albumin and nephrotic syndrome, in keeping with a large body of studies." (PMID 39739269, 2025). "These subgroups were based on the following: sex, age, type of surgery, use of laparoscopy, ASA grade, intraoperative blood loss, presence of diabetes mellitus, albumin level, and smoking habits." (PMID 40156892, 2025).
diabetes (continued). "Each risk factor (history of diabetes, type of chemotherapy, white blood cell count, and serum albumin level) is assigned a score based on the nomogram." (PMID 39773012, 2025). "Univariate logistic regression analysis revealed that several variables - including hemoglobin, platelet count, PCT, blood glucose, cholesterol, albumin, and diabetes mellitus - were significantly associated with bacteremia." (PMID 40792110, 2025). "Shapley Additive Explanations analysis consistently identified low albumin, impaired transfer ability, and the use of sedative-hypnotics or diabetes medications as major contributors to fall risk." (PMID 41343780, 2025). "For example, amino acids, creatinine, and albumin are common predictors for both diabetes and all‐cause dementia." (PMID 40717653, 2025). "Another study showed that higher ALB levels were associated with a reduced risk of microvascular complications in diabetes patients." (PMID 40391336, 2025). "We identified advanced age, comorbid diabetes, and low serum albumin levels as independent risk factors for OH." (PMID 41281282, 2025). "Higher hs-Tn levels were associated with older age, hypertension, diabetes, and greater urinary albumin–creatinine ratio." (PMID 40587684, 2025). "As clinical data scores increase—with albumin rising from -5 to 2, interferon from -5 to 6, and lymphocytes from approximately -2.8 to 5—the probability of high diabetes mellitus (DM) risk increases." (PMID 41384020, 2025). "APOM remained an independent inverse predictor of MACE risk even after further adjustment for diabetes, hypercholesterolemia, smoking, and serum albumin." (PMID 40047074, 2025). "One study investigating the albumin-to-fibrinogen ratio as a proxy for malnutrition also found that diabetes and an ASA classification ≥ 3 were significantly associated with malnourished patients." (PMID 40407919, 2025). "Worsening kidney function was reported in 126 patients (69.2%) and was associated with decreased serum albumin, diabetes mellitus, bilateral renal vein thrombosis and nephrotic syndrome." (PMID 39739269, 2025). "Other factors causing surgical site infections (SSIs) include diabetes mellitus, obesity, low serum albumin levels, renal and hepatic insufficiency." (PMID 40525001, 2025). "Diabetes showed a weak positive association, whereas cataract and higher levels of systolic blood pressure, total cholesterol, and serum albumin were independently linked to lower T-scores." (PMID 41049438, 2025). "Malnutrition assessed by CONUT is linked to higher diabetes prevalence in HF, influenced by altered albumin, cholesterol and lymphocyte levels." (PMID 40074368, 2025). "Our results indicate that certain parameters such as diabetes, low albumin levels, and prolonged duration of surgery are associated with a higher risk of infection." (PMID 41210930, 2025). "According to the American Diabetes Association, urine albumin excretion, urine albumin to creatinine ratio, and estimated glomerular filtration rate (eGFR) through a calculation that includes serum creatinine, age, and weight of the patient can also be used." (PMID 40822949, 2025). "In patients with T2DM, diabetes accelerates the loss of muscle strength, mass, and serum albumin, drawing attention to the protein and energy balance." (PMID 40297171, 2025). "Age, bilateral renal vein thrombosis, diabetes mellitus, sepsis, malignancy, serum albumin and hemoglobin levels were associated with all-cause mortality." (PMID 39739269, 2025). "Health status: diabetes, smoking, malnutrition, and low serum albumin levels were directly related to the risk of sarcopenia." (PMID 39839289, 2024). "The present study demonstrated that the fibrinogen-to-albumin ratio (FAR) is significantly associated with nerve conduction abnormalities in type 2 diabetes mellitus patients with DPN." (PMID 39744304, 2024).
diabetes (continued). "Logistic regression analysis revealed that a high SII, advanced age, diabetes, total albumin, and CRP concentration > 20.25 mg/L were independent risk factors for POD in older patients with intertrochanteric fractures." (PMID 38566241, 2024). "Clinically, DKD is diagnosed when there are no clear signs of kidney disease caused by factors other than diabetes, combined with increased urinary albumin excretion (>30 mg/g) and/or decreased GFR (<60 mL/min/1.73 m2)." (PMID 39840000, 2024). "Albumin changes were associated with acute heart failure among patients with male, age ≥ 75, smoker, diabetes, congestive heart failure, and PVD." (PMID 39902029, 2024). "After adjusting for age, diabetes, serum ALB, and abdominal aortic calcification score, the risk of ACM increased by 0.15 (95% CI = 1.085−1.228, P < .001) for every 1 m/s increment in PWV." (PMID 39121296, 2024). "Pathological modifications of albumin including glycation and cysteinylation are also associated with diabetes and liver disease." (PMID 38741158, 2024). "The RDW to albumin ratio (RAR), derived from RDW/albumin, was linked to multiple inflammatory diseases, such as diabetes and related complications, rheumatic conditions, sepsis, stroke, and heart failure." (PMID 39722824, 2024). "It identified that a BMI of ≥24 kg/m2, preoperative low albumin levels, preoperative malnutrition, and extended surgical duration are significant risk factors for postoperative incision infection, with diabetes also being a crucial risk factor." (PMID 39193402, 2024). "The most commonly reported predictors of UDI were cardiovascular disease, older age, cause of kidney disease, body mass index (BMI), cancer, diabetes, lower serum albumin, rate of eGFR decline and fewer nephrology visits prior to dialysis initiation." (PMID 39669010, 2024). "The AUC of RAR (AUC = 0.631; 95% CI: 0.588–0.675) for the risk of PAD in patients with diabetes was higher than that of albumin (AUC = 0.572; 95% CI: 0.526–0.618)." (PMID 38405142, 2024). "ROC curve revealed that systolic blood pressure, course of diabetes and urinary albumin had the highest diagnostic efficiency." (PMID 38545017, 2024). "Multiple analysis results showed that sex, diabetes, albumin level and NLR were independently associated with serum 25(OH)D level (p = .021, p = .015, p = .033, and p = .041, respectively)." (PMID 38652006, 2024). "The biochemical markers associated with survival in diabetes showed significantly lower vitamin D and magnesium while the hypertensive group was associated with decreased levels of vitamin D, bicarbonate, and albumin." (PMID 39310569, 2024). "Patients whose hemodialysis started earlier at a higher eGFR (eGFR >10.5 mL/min per 1.73 m^) are associated with more comorbidities (hypertension and diabetes), malnutrition (serum albumin lower than 3.5 g/dL), and risk of death." (PMID 38881801, 2024). "In summary, our present evidence shows that the main risk factors of CRI in hemodialysis were combined with diabetes, hemoglobin level, age, catheter indwelling time, serum albumin level, femoral vein catheter indwelling and catheterization times." (PMID 38589798, 2024). "In a multivariable model, age, sex, diabetes diagnosis, low albumin level and renal failure were associated with target organ damage." (PMID 38590318, 2024). "We used meta-analysis to find that the main risk factors of CRI in hemodialysis are combined-diabetes, age, hemoglobin level, catheter indwelling time, serum albumin level, femoral vein catheterization and catheterization times." (PMID 38589798, 2024). "Higher serum albumin levels in diabetic patients are significantly associated with a lower risk of microvascular complications related to diabetes." (PMID 38600468, 2024).